GRPR (gastrin releasing peptide receptor)
Diseases named in the same sentence as GRPR in open-access papers (continued):
Sharing a sentence is not in itself a finding about the gene and the disease.
tumor (continued). "GRPR protein expression was analyzed by immunohistochemistry in 80 tumor specimens and 10 cancer-free tissue samples." (PMID 41266536, 2025). "The heterodimer 177Lu-DOTA-RGD-BBN, targeting both αvβ3 and GRPR, showed good tumor uptake in PC-3 tumor models (5.88 ± 1.12% ID/g at 0.5 h), with decreasing retention over 48 h and favorable tumor-to-blood and T/M ratios." (PMID 40869454, 2025). "Gastrin-Releasing Peptide Receptor (GRPR)-targeted RLT agents bind to GRPR, a G-protein-coupled receptor implicated in tumour proliferation, migration, and metastasis." (PMID 41228206, 2025). "A faster clearance of [177Lu]Lu-TacsBOMB5 from PC-3 tumor xenografts was observed from the SPECT/CT images in comparison with the two novel GRPR agonists ([177Lu]Lu-LW01110 and [177Lu]Lu-LW01142) and [177Lu]Lu-AMBA." (PMID 40283887, 2025). "We also assessed their potential for PET imaging and targeted radiotherapy using a preclinical tumor model derived from GRPR-expressing PC-3 prostate cancer cells." (PMID 40006047, 2025). "In PC-3 xenografts, [177Lu]Lu-PKB2 and [177Lu]Lu-PKB3 demonstrated rapid background clearance and high GRPR-mediated tumor activity uptake at 2 h pi, exceeding activity uptake in the kidneys." (PMID 41231375, 2025). "[177Lu]Lu-PKB3 demonstrated 1.5-fold higher activity uptake in the tumor and pancreas (a GRPR-expressing organ) compared to [177Lu]Lu-PKB2." (PMID 41231375, 2025). "Our observations on hypoxia upregulated GRPR expression are consistent with previous studies showing that hypoxia can modulate G protein–coupled receptor (GPCR) expression in tumours." (PMID 41226822, 2025). "These biodistribution results in NMRI mice support further in vivo characterization of [18F]MeTz-PEG2-RM26 (8a) in mice bearing GRPR-positive PC-3 tumours." (PMID 40138074, 2025). "This approach improved tumor-to-blood ratios and reduced background signal, illustrating a novel avenue for optimizing GRPR-targeted imaging." (PMID 41251982, 2025). "The better tumor uptake of [177Lu]Lu-LW01110 and [177Lu]Lu-LW01142 compared with the GRPR antagonist [177Lu]Lu-TacsBOMB5 also contributed to their better tumor/blood and tumor/muscles uptake ratios." (PMID 40283887, 2025). "All peptide radioligands had a rapid clearance from the background tissues, with the highest activity uptake found in the implanted tumours, the kidneys and to a lesser extent the GRPR-rich pancreas." (PMID 40745236, 2025). "The DOTA-carrying peptide showed higher GRPR-affinity and greater PC-3 tumor uptake than its DOTAGA-carrying counterpart, underlining the importance of the local charge and/or complex-conformation at the N-terminus of GRPR-targeting peptides." (PMID 41231375, 2025). "In the context of dual-targeting agents—especially those directed at both integrin αvβ3 and 64Cu-GRPR—this approach has demonstrated favorable pharmacokinetics and strong tumor uptake, offering high-contrast imaging potential." (PMID 40869454, 2025). "The examined GRPR antagonist demonstrated a high absorption by the tumor at extremely low absorption by healthy tissues, which gives a high tumor-to-background tissue contrast during PET-examination." (PMID 39539754, 2024). "Specifically, 177Lu-labeled GRPR antagonists have been developed and show good safety and anti-tumor effects." (PMID 38880858, 2024). "While the Gly11/Sar11 substitution was pursued for increasing in vivo stability, the introduction of basic residues in the linker aimed to improve receptor affinity and enhance the uptake in GRPR-expressing cells and tumor models in mice." (PMID 38675174, 2024). "Conversely, in the MDA-MB-435 (GRPR-) cell line, the tumor uptake at 1 h for 64Cu-NOTA-RGD-BBN and 68Ga-NOTA-RGD-BBN was 1.84 ± 0.44%ID/g and 2.24 ± 0.73%ID/g, respectively." (PMID 38708130, 2024). "On the other hand, [111In]In-AU-SAR-M3 demonstrated the lowest tumor uptake, although its GRPR-affinity and in vivo stability were comparable with [111In]In-AU-SAR-M1." (PMID 38366299, 2024).
tumor (continued). "When the biodistribution profilesof the two radiopeptides weretested in mice bearing GRPR-expressing xenografts of PCa origin, bothconjugates had high pancreatic and tumor uptakes at 1 h pi." (PMID 38680331, 2024). "GRPR-silenced A549-FLuc cells were injected intravenously into the lateral tail veins of mice, and tumor metastasis was monitored weekly via luminescence imaging." (PMID 39768218, 2024). "Both radiopeptides had a rapid clearancefrom the background, including from the GRPR-expressing organs suchas small intestines, stomach, and pancreas, while tumor values wereretained more or less on the same level at 3 h pi." (PMID 38680331, 2024). "They focused on the impact of combining 44gSc and 68 Ga-labeled DOTA complexes with the GRPR antagonist BBN2 on GRPR affinity in vitro, as well as their biodistribution and tumor uptake in MCF7 and PC-3 models." (PMID 38279185, 2024). "The capability of 68Ga-labeled TacBOMB2 derivatives to target GRPR in vivo was evaluated by PET imaging and biodistribution studies in mice bearing GRPR-expressing PC-3 tumor xenografts." (PMID 38305955, 2024). "Nowadays, a lot of radionuclide-labeled GRPR agonists/antagonists have been developed and applied in tumor imaging and treatment." (PMID 38279185, 2024). "The tumor and pancreatic uptake were shown to be GRPR-specific during an additional GRPR-blockade study in the case of [111In]In-AU-SAR-M1." (PMID 38366299, 2024). "In both cases, there was an approximate 80% decrease in pancreatic radio-uptake and a 36%–48% decrease in tumor uptake, demonstrating the strong affinity of these compounds for tissues expressing GRPR." (PMID 38708130, 2024). "In order to enhance therapeutic efficacy, the search for GRPR-radioantagonists with improved metabolic stability and prolonged retention times on tumor-lesions is currently ongoing." (PMID 38366299, 2024). "In the case of GRPR, the distribution of tumor cells was weakly and positively correlated with the GRPR expression (Spearman ρ = 0.198, p<0.0001)." (PMID 39629134, 2024). "RGD and bombesin have shown promise as tumor imaging agents, targeting integrin αvβ3 and GRPR, respectively." (PMID 38279185, 2024). "Studies have shown that GRPR antagonists have superior properties to those of GRPR agonists, including higher tumor uptake and lower accumulation in physiologic GRPR-expressing healthy tissues." (PMID 39327021, 2024). "The resulting radioligands demonstrated good GRPR-affinity and cell uptake, high tumor accumulation and rapid clearance from the background in mice, even from the GRPR-rich pancreas." (PMID 38366299, 2024). "It cannot be excluded that GRPR-mediateduptake of [111In]In-ABD-RM26 Gen 2A in tumors constitutesonly part of the overall tumor uptake and the enhanced permeabilityand retention (EPR) effect of the albumin-ABD-RM26 adduct constitutesthe rest." (PMID 39220525, 2024). "Next to high tumor uptake, significant uptake was observed in the GRPR-expressing pancreas and the kidneys, the latter as a consequence of renal excretion." (PMID 37640941, 2024). "The tumor location and Gleason score of prostate tissue were evaluated, and GRPR expression was determined through in vitro autoradiography." (PMID 38279185, 2024). "These analogues have demonstrated GRPR-specific PET imaging capabilities in small animal tumor models, but they came with various advantages and disadvantages." (PMID 38279185, 2024). "Tumor target drug gastrin-releasing peptide receptor (GRPR) antagonist RC-3095 reduces the secretion of NGF in COAD cells, suggesting that the reduction of neurotrophin secretion is a potential mechanism for the anti-proliferation effect of GRPR antagonists." (PMID 38694509, 2024). "Several studies have demonstrated that radiolabeled GRPR antagonists achieve higher tumor uptake and retention in comparison with agonists, despite their significantly inferior internalization in tumor cells." (PMID 38366299, 2024).
tumor (continued). "PSMA mRNA levels in non-tumor areas were also significantly higher than GRPR mRNA levels (p < 0.05)." (PMID 37719014, 2023). "GRPR antagonists, in contrast, appear to combine optimal tumor targeting properties with improved pharmacokinetics and a better safety profile, which prompted the development of several molecules with translational potential." (PMID 38020178, 2023). "Stimulation of GRPR promotes smooth muscle contraction in the GI tract and has been shown to increase cancer cell proliferation and tumour growth." (PMID 36672390, 2023). "After administration of the tracer (25–50 μg peptide/dose) several pathological lesions including lymph nodes, liver and bone metastasis were visualized and [68Ga]Ga-AMBA proved to be a valuable tool to assess GRPR tumor expression status." (PMID 38020178, 2023). "This modification resulted in significant improvement in metabolic stability of circulating [111In]In-AU-RM26-M1 and translated into better uptake and retention in a GRPR-positive tumor mice model." (PMID 37509170, 2023). "GRPR antagonists have shown superior tumor uptake and pharmacokinetic properties compared to agonists." (PMID 37584725, 2023). "GRP and gastrin-releasing peptide receptor (GRPR) also appear to play a role in human carcinogenesis and tumor proliferation." (PMID 36832085, 2023). "Extensive structure-activity relationship (SAR) studies have been conducted in GRPR-expressing cells and tumor-bearing animals, with PC-3 cells and PC-3 xenografts in mice prevailing as a model." (PMID 37242457, 2023). "Gastrin releasing peptide (GRP) and its receptor (GRPR) are morphogenetic factors, which keep tumor cells at high degree of differentiation and reduce tumor metastasis ability." (PMID 37228820, 2023). "They reported that the AuNPs were ornamented with BBN (Bombesin) analogues, a peptide that is bioactive and has a very high affinity to GRPr (Gastrin Releasing Peptide receptor) which are found in many kinds of tumours or cancers." (PMID 38112849, 2023). "With good tumor uptake and tumor-to-background uptake ratios, [68Ga]Ga-TacBOMB2 is promising for detecting GRPR-expressing tumors." (PMID 36838968, 2023). "During preclinical evaluation [68Ga]Ga/[177Lu]Lu-NeoBOMB1 showed high receptor affinity and GRPR-specific cell-uptake, high metabolic stability and high and prolonged tumor uptake in GRPR-expressing tumors in mice." (PMID 37242457, 2023). "The comparison between the biodistribution of [111In]In-AU-RM26-M1 and [111In]In-DOTAGA-PEG2-RM26 over time indicated a tendency of the Sar11-radioligand for improved GRPR-mediated tumor uptake." (PMID 37509170, 2023). "The action of proteases, such as neprilysin (NEP), on GRPR radioantagonists was shown to impair their bioavailability compromising the tumor uptake." (PMID 37509170, 2023). "This material showed a great affinity for GRPR-positive cells in vitro and increased tumor uptake in vivo upon intravenous injection, hence leading to improved tumor contrast in MRI images." (PMID 36834867, 2023). "GRPR is overexpressed in several malignancies, and, in tumor cells, it is predominantly involved in cell proliferation and cell cycle progression." (PMID 38067350, 2023). "Tumour absorbed doses were found to be therapeutically relevant, whereas rapid clearance from normal GRPR-rich organs, such as the pancreas, was confirmed." (PMID 39355052, 2023). "Aminobenzoyl–bombesin analogue (4-aminobenzoyl-Q-W-A-V-G-H-L-M-NH2, AMBA) is regarded as a highly valuable imaging agent in the nuclear medical diagnostics of GRPR-upregulated tumours." (PMID 37108559, 2023). "As expected, in both groups pancreatic uptake was found significantly higher than in the GRPR-blocked group of PC-3 tumor-bearing mice." (PMID 37509170, 2023).
tumor (continued). "[68Ga]Ga-BQ7812 demonstrated specific and rapid binding to its targets and its biodistribution pattern was characterised by an initial elevated activity uptake in the tumour (PSMA/GRPR positive), kidneys (PSMA positive), and pancreas (GRPR positive)." (PMID 36672390, 2023). "Over-expression of GRPR in PCa has been found in both primary tumours as well as lymph nodes and bone metastasis." (PMID 36672390, 2023). "Angiogenesis-related cell-surface molecules, including integrins, aminopeptidase N, vascular endothelial growth factor, and gastrin-releasing peptide receptor (GRPR), play a crucial role in tumour formation." (PMID 37108559, 2023). "In vivo studies, performed in female SCID mice bearing T47D xenografts, revealed a rapid blood clearance and high GRPR-mediated uptake in the pancreas and tumor, with the tumors being clearly visualized by microPET imaging studies." (PMID 38020178, 2023). "Positively charged 68Ga-DATA5m-RM2 provided a high tumor uptake, high image contrast and good capability of targeting GRPr." (PMID 37285007, 2023). "Bombesin (BBN), a 14 amino acid peptide, and its analogues based on this 14-amino acid backbone sequence (e.g., BBN 6–14) have been investigated as targeting ligands for diagnosis and therapy of GRPR-positive tumours using several different radionuclides." (PMID 37241862, 2023). "Surprisingly, we found that inhibited GRPR signaling by low dose (10 μM) IRDye800‐RM26 impeded tumor cell invasion." (PMID 37476052, 2023). "Biodistribution studies in xenografts-bearing Balb/c nude mice confirmed a similar tumor uptake in the two cancer models and optimal in vivo stability, highlighting these molecules as promising candidates for GRPR PET-imaging of BC and PC." (PMID 38020178, 2023). "The immunohistochemical staining results show positive GRPR expressions in three out of five tumor samples in PCa patients (60%) and in five of seven tumor tissue in BCa patients (71.4%)." (PMID 36980517, 2023). "The aim was to design a glioma-targeting nanocarrier with the ability to cross the blood–brain barrier and deliver the therapeutic of choice to the GRPR-overexpressing cells of the tumor." (PMID 36834867, 2023). "Ultimately, we aim to improve surgical efficacy for patients with GRPR-expressing solid tumors and thereby reduce the likelihood of tumor recurrence." (PMID 37046825, 2023). "We demonstrated that our concept of modifying the pharmacophore of 99mTc-labeled GRPR antagonists at the Gln7-Trp8 results in improved tumor-to-organ ratios in the abdominal area at early time points." (PMID 36145354, 2022). "Co-injection with an excess of unlabeled NeoB resulted in a strongly decreased uptake level of the probes in the GRPR-positive tumor and organs, indicating receptor specificity." (PMID 35057090, 2022). "Biodistribution studies with this derivative have further confirmed the promising cellular results with a good and persistent uptake in the tumor and the GRPR-expressing tissues." (PMID 36559063, 2022). "The GRPR positive tumor-targeting potential of [68Ga]Ga-NODAGA-AMBA and [44Sc]Sc-NODAGA-AMBA was investigated by preclinical PET imaging 60 and 120 min after intravenous radiotracer injection." (PMID 36077458, 2022). "The ease and stability of the radiochemistry, favorable biodistribution, and the positive tumor inhibition demonstrate the suitability of this copper-based theranostic agent for clinical assessment in the treatment of cancers expressing GRPR." (PMID 35745647, 2022). "Imaging studies with GRPR-targeted radiotracers have demonstrated high tumor uptake and excellent visualization of tumor lesions in cancer patients." (PMID 35057090, 2022). "In general, GRPR antagonists are cleared more rapidly from the pancreas than from the tumor over time, which is why tumor-to-pancreas ratios at 4 or 24 h p.i. are noticeably higher than at 1 h p.i.." (PMID 36145354, 2022).
tumor (continued). "Nonetheless, GRPR antagonists have demonstrated superior pharmacokinetic properties and high tumor accumulation in several in vivo models, emerging as a valuable alternative in the development of GRPR-targeting radiopharmaceuticals." (PMID 36559063, 2022). "The uptake was GRPR-specific, since reduced tumor uptake was observed when the GRPR was blocked using an excess of unlabeled NeoB." (PMID 35057090, 2022). "They presented the reduction of the radiopharmaceutical accumulation in the group of PC-3 tumor-bearing nude mice injected with the GRPR-blocking agent 30 min prior to the tracer administration compared to those pets that did not receive the blocking ligand." (PMID 36077458, 2022). "After the development of these compounds, we assessed the effect of the dye attachment on the stability and affinity for GRPR in vitro and the tumor-targeting capability and biodistribution in vivo." (PMID 35057090, 2022). "Co-injection of an excess of unlabeled NeoB led to a decreased uptake in the tumor and the GRPR-expressing organs, such as the pancreas." (PMID 35057090, 2022). "[99mTc]Tc-RGD-BBN, which targets both integrin αvβ3 and GRPR, was developed to improve tumor detection over mono-targeted imaging agents." (PMID 35565232, 2022). "Current radiolabeled gastrin-releasing peptide receptor (GRPR) ligands usually suffer from high accumulation in GRPR-positive organs (pancreas, stomach), limiting tumor-to-background contrast in the abdomen." (PMID 36145354, 2022). "recently reviewed the present developments on the GRPR-targeted pharmaceuticals for human tumor imaging." (PMID 35992794, 2022). "Here, the specificity of our probes for the GRPR as a tumor target was demonstrated by a pilot blocking study using a single animal." (PMID 35057090, 2022). "GRPR also constitutes a promising biomolecular target in nuclear oncology for a theragnostic approach combining tumor imaging therapy." (PMID 33801382, 2021). "This more pronounced effect of [177Lu]Lu-NeoB on tumor regression observed on 400 pmol in comparison to 800 pmol group is in accordance with the higher [177Lu]Lu-NeoB uptake in GRPR tumors." (PMID 33801382, 2021). "More interestingly, multi-dimensional scaling revealed that PSMA and GRPR are inversely related, confirming that both measures can be used as a reliable indicator of the size of the tumor tissue." (PMID 33854977, 2021). "During this initial period, several SPECT and PET GRPR-directed agents were designed for tumor diagnosis with a strong focus on the choice of linker and chelator to optimize pharmacokinetics, and a few of them were tested in patients." (PMID 34830920, 2021). "In all cases radioligand uptake was receptor-mediated, as suggested by the significant reduction (p < 0.001) of tumor and pancreas values during in vivo GRPR-blockade by co-injection with excess [Tyr4]BBN." (PMID 34680243, 2021). "[99mTc]Tc-maSSS-PEG2-RM26 outperformed [99mTc]Tc-maSES-PEG2-RM26 in terms of GRPR affinity, with a lower dissociation constant (61 pM vs 849 pM) and demonstrating higher tumor uptake." (PMID 33573232, 2021). "While biodistribution studies explain the higher tumor uptake and the better tumor/non-tumor ratio for the antagonist ligand, microPET/CT images clearly confirm that the agonist is a much better GRPR-targeted molecular imaging agent." (PMID 34830000, 2021). "The most profound decrease (> 98%) was observed in the GIST tumor (0.3 ± 0.1 vs 19.1 ± 3.9% ID/g) and the pancreas (0.1 ± 0.0 vs 8.5 ± 2.0% ID/g), indicating GRPR specificity." (PMID 33801382, 2021). "This fact has been illustrated in a recent report, whereby cysteine cathepsin inhibitors are coupled to GRPR-peptides leading to improved tumor retention via endolysosomal trapping." (PMID 34680243, 2021). "Rapid washout was observed even from GRPR-rich organs, such as the pancreas, resulting in improved tumor-to-background ratios over time, a feature characteristic for most GRPR radioantagonists thereafter." (PMID 34830920, 2021).